RBM27 (RNA binding motif protein 27)
Description:
May be involved in the turnover of nuclear polyadenylated (pA+) RNA.
Synonyms: KIAA1311; ARRS1; Psc1; ZC3H20
Tractability: PROTAC: ubiquitination databases record sites on it; its protein half-life has been measured.
Gene: Protein-coding gene on chromosome 5 (146,203,550 to 146,289,223, forward strand). Ensembl gene ENSG00000091009.
Subcellular location: Cytoplasm; Nucleus speckle
Subcellular location (Human Protein Atlas): Nuclear speckles
Pathways (Reactome):
Metabolism of RNA: Nuclear RNA decay
Gene Ontology:
Molecular function: RNA binding; metal ion binding; nucleic acid binding
Biological process: RNA catabolic process
Cellular component: nucleoplasm; nucleus; cytoplasm; nuclear speck
Genetic constraint (gnomAD): Loss-of-function variants: 17 observed, 108.98 expected, observed/expected ratio (o/e) 0.16, 90% interval 0.11 to 0.23. The upper end of that interval is the gene's LOEUF score, 0.23, which puts it in group 1 of 6, group 1 being the genes least tolerant of losing a copy. Missense variants: 901 observed, 1,153.9 expected, observed/expected ratio (o/e) 0.78, 90% interval 0.74 to 0.82. Synonymous variants: 437 observed, 399.15 expected, observed/expected ratio (o/e) 1.09, 90% interval 1.01 to 1.18.
Homologues: Orthologues: chimpanzee RBM27 (99% identical), macaque RBM27 (99% identical), dog RBM27 (97% identical), rabbit RBM27 (97% identical), mouse Rbm27 (95% identical), rat Rbm27 (95% identical), pig RBM27 (88% identical), guinea pig RBM27 (80% identical), zebrafish rbm27 (51% identical), Drosophila melanogaster swm (27% identical), Caenorhabditis elegans rbm-26 (22% identical). Paralogues in human: RBM26 (45% identical).
Diseases named in the same sentence as RBM27 in open-access papers:
RBM27 is named in the same sentence as 8 diseases in open-access papers, as found by Europe PMC text mining. Sharing a sentence is not in itself a finding about the gene and the disease. The quoted sentences say what the papers report.
autism (1 paper, 2024). Persistent deficits in social interaction and communication and interaction as well as a markedly restricted repertoire of activity and interest as well as repetitive patterns of behavior. "These phenotypes are induced by an rbm-26 null allele as well as by alleles that are equivalent to autism-associated de novo missense variants in RBM27, suggesting that these are likely gene-disrupting variants in humans." (PMID 39480871, 2024). "The RBM27 (rbm-26/Swm/Rmn1) gene encodes an RNA-binding protein and is considered an autism candidate gene by the Simons Foundation Autism Research Initiative (SFARI)." (PMID 39480871, 2024). "Moreover, the identity of RBM27 as an autism candidate gene is based on de novo missense mutations that have not been tested for gene-disrupting activity." (PMID 39480871, 2024). "Here, we address this question through the investigation of rbm-26, the Caenorhabditis elegans ortholog of the RBM27 autism candidate gene, which encodes an RNA-binding protein whose role in neurons is unknown." (PMID 39480871, 2024). "RBM27 has been identified as a candidate autism gene by the SFARI." (PMID 39480871, 2024). "The potential association of RBM27 with autism is based on the identification of 5 de novo variants in probands with autism or other neurodevelopmental disorders, but none in unaffected siblings." (PMID 39480871, 2024).
cancer (2 papers, 2019 to 2022). A tumor composed of atypical neoplastic, often pleomorphic cells that invade other tissues. "To date, no studies have implicated RBM27, SEC24B, or SSH2 in CRC or cancer development." (PMID 30809968, 2019).
RBM27 also shares sentences with these, for which no sentence is quoted: tumor (3 papers); breast carcinoma (1); breast tumor (1); genetic disease (1); neurodevelopmental disorder (1); Prader-Willi syndrome (1).